SOCS1 (suppressor of cytokine signaling 1)
Diseases named in the same sentence as SOCS1 in open-access papers (continued):
Sharing a sentence is not in itself a finding about the gene and the disease.
liver diseases (6 papers, 2010 to 2021). "It was determined that the deficiency of SOCS1 could induce severe hepatic disorders." (PMID 32128089, 2019). "Recent studies on humans suggest that SOCS1 is involved in the development of various liver disorders in humans." (PMID 20862390, 2010). "We will further discuss the importance of SOCS1 in the pathogenesis of liver diseases." (PMID 20862390, 2010). "Studies using animal models suggest that inadequate induction or impaired expression of SOCS1 may induce liver diseases in humans." (PMID 20862390, 2010). "Thus far, although inactivating mutations in SOCS1 gene were detected in a subset of lymphoma cells, such mutations have not been observed in hepatic disorders." (PMID 20862390, 2010). "Future studies on SOCS1 and other SOCS proteins will provide insight into the pathobiology of human liver diseases and develop new strategies for the treatment of acute and chronic liver diseases." (PMID 20862390, 2010). "Thus, SOCS1 and other SOCS proteins are potential targets for the therapy of human liver diseases." (PMID 20862390, 2010).
mycosis fungoides (6 papers, 2021 to 2024). Classical mycosis fungoides is the most common type of mycosis fungoides (MF), a form of cutaneous T-cell lymphoma, and is characterized by slow progression from patches to more infiltrated plaques and eventually to tumors. "The results also indicated that single copy loss of Socs1 in combination with sustained inflammation is insufficient to start a phenotype resembling early stage mycosis fungoides within eight weeks in these mice." (PMID 36505769, 2022). "Studies have also reported the loss of SOCS1 in early-stage mycosis fungoides patients." (PMID 37664523, 2023). "In mycosis fungoides, SOCS1 was identified as one of the highly recurrently deleted tumor suppressors and the gene rearrangements of SOCS1 were already present in the earliest stages of MF." (PMID 36505769, 2022). "To elaborate on the function of SOCS1 and other identified genes in mycosis fungoides, in particular in the initiating events, we aim to use mouse models." (PMID 36505769, 2022). "This coincides with the recent genomic analysis of mycosis fungoides which identified SOCS1 and one of the frequently deleted tumour suppressors in this disease; a one copy deletion of SOCS1 has been identified in lesions exhibited in early stage Sézary syndrome." (PMID 39676878, 2024). "In summary, this long-term experiment confirmed that Socs1-knockout in skin-resident CD4+ T cells in a protracted contact-allergic reaction results in an autonomous skin inflammation with features of early-stage mycosis fungoides." (PMID 37664523, 2023). "Genetic deletion of SOCS1, as a negative regulator of JAK–STAT signaling, has recently been detected in skin biopsies of patients with tumor‐stage mycosis fungoides." (PMID 36341492, 2022). "Thus, we clearly demonstrate that mice with one-copy deletion of Socs1 in skin resident CD4+ T cells in protractedly inflamed skin lead up to an autonomous inflammation and the features of early-stage mycosis fungoides." (PMID 37664523, 2023). "Deletion of SOCS1, a negative regulator of the JAK family proteins, which was seen in a colonic CD4+ iTLPD, is a recurrent abnormality in a variety of T-cell lymphomas and more commonly reported in mycosis fungoides." (PMID 34205136, 2021). "Considering the grave effects caused by SOCS1 absence and more particularly one-copy deletion of SOCS1 in CD4+ T cells in MF, the present long-term in vivo experiments focused on the impact of conditional Socs1 knockout in CD4+ T cells to mimic early-stage mycosis fungoides." (PMID 37664523, 2023). "Recent detailed genomic analysis of mycosis fungoides (MF) identified suppressor of cytokine signaling 1 (SOCS1), an inhibitor of JAK/STAT signaling, as one of the frequently deleted tumor suppressors in MF, and one-copy deletion of SOCS1 was confirmed in early-stage MF lesions." (PMID 37664523, 2023).
osteosarcoma (6 papers, 2022 to 2025). A usually aggressive malignant bone-forming mesenchymal neoplasm, predominantly affecting adolescents and young adults. "Western blot results indicate that miR-331-3p affects the occurrence and development of osteosarcoma through the SOCS1/JAK2/STAT3 pathway." (PMID 36199788, 2022). "Moreover, miR-331-3p affected the occurrence and development of osteosarcoma by targeting the SOCS1/JAK2/STAT3 signaling pathway." (PMID 36199788, 2022).
atopic dermatitis (5 papers, 2018 to 2025). "Atopic dermatitis, in an SOCS1-dependent manner, decreased the expression of iNOS while increasing the expression of CD163 in BALB/c mouse." (PMID 30459600, 2018). "Atopic dermatitis increased the expression levels of SOCS1, TGaseII, COX-2, histone deacetylase 3 (HDAC3), and MCP1 in BALB/c mouse in an MIP-2-dependent manner." (PMID 30459600, 2018). "Atopic dermatitis increased the expression of CXCL13 in the sera of BALB/c mice in a SOCS1-dependent manner." (PMID 30459600, 2018). "Atopic dermatitis decreased the expression of IL-10 in BALB/c mouse in an SOCS1-dependent manner." (PMID 30459600, 2018). "Based on the suppressor of cytokine signaling 1 (SOCS1)/Janus kinase (JAK)/signal transducer and activator of transcription 3 (STAT3) pathway, the mechanism of oxymatrine in the treatment of atopic dermatitis (AD) was preliminarily explored in this study." (PMID 36703757, 2022). "Atopic dermatitis increased the expression levels of IL-4, IL-13, IL-6, IL-17, IFNγ, and TNFα but decreased the expression of IL-10 in BALB/c mouse, in an SOCS1-dependent manner." (PMID 30459600, 2018). "Atopic dermatitis increased the expression levels of MIP-2, COX-2, HDAC3, and MCP1 in BALB/c mice in a SOCS1-dependent manner." (PMID 30459600, 2018). "Atopic dermatitis increased the expression levels of CD163, SOCS1, MIP-2, COX-2, HDAC3, COX-2, and MCP1 but decreased the expression of iNOS in a CXCL13-dependent manner." (PMID 30459600, 2018). "Atopic dermatitis increased the expression levels of T-bet and GATA-3 but decreased the expression of Foxp3 in BALB/c mouse, in an SOCS1-dependent manner." (PMID 30459600, 2018). "Atopic dermatitis increased the expression levels of T-bet and GATA-3 [transcription factors of T-helper 1 (Th1) and T-helper 2 (Th2) cells, respectively] but decreased the expression of Foxp3, a transcription factor of regulatory T (Treg) cells, in an SOCS1-dependent manner." (PMID 30459600, 2018).
autoimmune uveitis (5 papers, 2019 to 2024). An autoimmune form of uveitis (disease). "SOCS1 inhibits lymphocyte recruitment into the retina and rats and mice with targeted over-expression of SOCS1 in the retina are partially protected from experimental autoimmune uveitis." (PMID 31344857, 2019). "Using a peptide with an amino-terminal palmitoyl-lysine adduct for cell permeation, Egwuagu and colleagues also showed that topical application of SOCS1-KIR could prevent pathology in rodent models of autoimmune uveitis, if delivered from the time of immunization." (PMID 39104531, 2024). "Furthermore, a modified version of SOCS1-KIR, named R9-SOCS1-KIR, containing a N-terminal poly-arginine sequence for penetration into plasma membrane, ameliorated autoimmune uveitis in mice." (PMID 38975347, 2024).
co-infection (5 papers, 2014 to 2024). "Galectin-3 modulates SOCS1 expression, which may contribute to the overall inflammatory response, and can influence RIG-I expression during co-infection, leading to dysregulated expression and release of pro-inflammatory cytokines." (PMID 37298569, 2023). "Inhibition may be due to the prior presence of negative regulatory factors such as SOCS-1 and IFN-β in the system, which may be induced in some earlier phase of infection or because of a co-infection." (PMID 25255432, 2014).
head and neck squamous cell carcinoma (5 papers, 2021 to 2023). A squamous cell carcinoma that arises from any of the following anatomic sites: lip and oral cavity, nasal cavity, paranasal sinuses, pharynx, larynx, and salivary glands. "Ferroptosis-related gene SOCS1, has become a biomarker for the diagnosis or prognosis of many diseases, such as tuberculosis, AML and head and neck squamous cell carcinoma (HNSCC)." (PMID 36072803, 2022).
laryngeal carcinoma (5 papers, 2013 to 2022). Carcinoma that arises from the laryngeal epithelium. "Our previous study indicated that miR-155 can promote the migration and invasion of laryngeal cancer through targeting SOCS1." (PMID 31718618, 2019). "Our previous study showed that SOCS1 inhibited the laryngeal cancer’s migration and invasion through targeting Stat3." (PMID 31718618, 2019). "Another study demonstrated that the expression of SOCS1 and LR4-NFκB pathway molecules had a strong association with the aggressiveness of laryngeal carcinoma." (PMID 23437123, 2013). "Suppressor of cytokine signaling 1 (SOCS1), a regulator of cytokine-mediated innate and adaptive immunity, has been reported to inhibit the TLR4–NF-κB pathway in laryngeal carcinoma." (PMID 31318878, 2019).
neuroendocrine tumor (5 papers, 2009 to 2016). "SOCS1 expression is also higher in IFN-resistant neuroendocrine tumor cells and siRNA inhibition of SOCS1 expression enhances their IFN-responsiveness." (PMID 26788993, 2016). "Other reports have demonstrated that silencing of SOCS1 can enhance the anti-tumor activity of type I or type II IFNs by regulating apoptosis in neuroendocrine tumor cells." (PMID 20398276, 2010). "As for SOCS1 some scholars have demonstrated that SOCS1 plays an important role in degrading IFN resistance of neuroendocrine tumor cells through negative regulation of Jak/STAT signaling pathway." (PMID 20003295, 2009).
ulcerative colitis (5 papers, 2019 to 2024). An inflammatory bowel disease involving the mucosal surface of the large intestine and rectum. "TUG1 showed a protective effect on intestinal tissue, both in-vivo and in-vitro, in ulcerative colitis by inhibiting inflammation-induced ROS and pro-inflammatory cytokines through targeting miR-142-3p and enhancing SOCS1 production." (PMID 40176927, 2024). "The expression levels of SOCS1 and miR-222-3p in the colonic mucosa tissues of patients with ulcerative colitis and healthy controls were determined by reverse transcription-quantitative polymerase chain reaction." (PMID 35946880, 2022). "To further explore the relationship among SCFAs, JAK2, STAT3, and SOCS1 and the development of ulcerative colitis, we initially observed changes in inflammation-related indicators in vivo." (PMID 32038241, 2019). "Additionally, miR-222-3p expression was upregulated in ulcerative colitis patients (P = 5.16E−10), while SOCS1 (P = 2.75E−10) and VDR (P = 52.5E−9) expression was downregulated in ulcerative colitis patients." (PMID 35946880, 2022). "Western blot analysis and qPCR analysis in IEC6 cells stimulated by IL-6 in vitro revealed that EHLJ7 could cooperate with butyrate to exert its anti-ulcerative colitis effect by inhibiting the activation of JAK2/STAT3/SOCS1 pathway." (PMID 32038241, 2019). "MiR-222-3p targets SOCS1 to aggravate the inflammatory response by suppressing VDR and activating STAT3 signaling in ulcerative colitis." (PMID 35946880, 2022). "MiRNA-31-5p is also elevated in inflamed ulcerative colitis mucosa, where it suppresses the expression of signal transducer and activator of transcription 6 (STAT6), suppressor of cytokine signaling 1 (SOCS1), and eotaxin-3 (CCL26) via downregulating the IL-13 receptor α-1 (IL13Rα-1) gene." (PMID 37559103, 2023). "Further study indicated that EHLJ7 could cooperate with butyrate to exert its anti-ulcerative colitis effect by inhibiting the activation of janus kinase 2 (JAK2)/signal transducer and activator of transcription 3 (STAT3)/suppressor of cytokine signaling 1 (SOCS1) pathway." (PMID 32038241, 2019).
AIDS (4 papers, 2015 to 2024). A syndrome resulting from the acquired deficiency of cellular immunity caused by the human immunodeficiency virus (HIV). "In particular, an increased level of SOCS1 protein has been associated with an increase of HIV-1 viral load and fast progression to AIDS." (PMID 26090662, 2015). "Further studies utilizing knockdown or overexpression of SOCS1 or SOCS3 would elucidate this possibility for experimental MCMV retinitis and/or AIDS-related HCMV retinitis." (PMID 31031749, 2019). "Herein we discuss these human and animal herpesviruses currently known to affect SOCS proteins in various in vitro and in vivo model systems, with particular emphasis on SOCS1 and SOCS3 expression during experimental MCMV retinitis, a mouse model used to study AIDS-related HCMV retinitis." (PMID 31031749, 2019). "If SOCS1 and/or SOCS3 contribute to the pathogenesis of this disease, then their inhibition in HIV/AIDS patients with HCMV retinitis could prevent further damage to affected eyes and/or protect the contralateral eye from vision loss." (PMID 31031749, 2019). "It remains a possibility that the immunosuppressive effect of SOCS1 and/or SOCS3 may play a protective role against a potential immunopathology of experimental MCMV retinitis or AIDS-related HCMV retinitis." (PMID 31031749, 2019). "Although many questions remain, SOCS1 and/or SOCS3 may play promising roles in the balance of this phenomenon, potentially revealing themselves as novel therapeutic targets to improve the management and/or prevention of AIDS-related HCMV retinitis." (PMID 31031749, 2019).
chronic hepatitis C (4 papers, 2010 to 2017). "In chronic hepatitis C patients receiving pegylated-interferon/ribavirin, SOCS-1 promoter methylation is closely associated with treatment response." (PMID 28915645, 2017). "Finally, we measured SOCS1 mRNA expression levels in peripheral blood mononuclear cells (PBMCs) with or without IFN-α treatment from 48 chronic hepatitis C patients and we found the baseline SOCS1 expression levels are higher in treatment non-responders than in responders before IFN-α treatment." (PMID 26193702, 2015).
cytomegalovirus retinitis (4 papers, 2017 to 2024). Infection of the retina by cytomegalovirus characterized by retinal necrosis, hemorrhage, vessel sheathing, and retinal edema. "Because macrophages contribute prominently to the inflammation observed during cytomegalovirus retinitis and macrophages produce SOCS1 and SOCS3 during MAIDS-related MCMV retinitis, monolayers of mouse macrophages were used in these studies." (PMID 34358000, 2021). "It remains unclear, however, whether virus-induced stimulation of SOCS1 and/or SOCS3 is protective or pathogenic in the eye during MAIDS-related MCMV retinitis, an uncertainty that continues to motivate further investigations of SOCS and cytomegalovirus retinitis pathogenesis." (PMID 34358000, 2021).
endotoxemia (4 papers, 2013 to 2023). "By suppressing LPS-induced production of SOCS1 (an inherent negative feedback system), upregulation of miR-155 would be expected to augment the effects of inflammatory cytokines in endotoxemia." (PMID 28552958, 2017).
follicular lymphoma (4 papers, 2019 to 2022). Follicular lymphoma is a form of non-Hodgkin lymphoma characterized by a proliferation of B cells whose nodular structure of follicular architecture is preserved. "Of these, mutations in CREBBP, KMT2D, TNFRSF14 and RRAGC were enriched in follicular lymphoma, and those of BTG2, HLA-A, PIM1, IGLL5, SOCS1, CD83 and SGK1 were enriched in DLBCL." (PMID 33945543, 2021). "Recurrent mutations of genes involved in epigenetic regulation (e.g. KMT2D, CREBBP, and EZH2), JAK-STAT pathway (e.g. SOCS1, STAT6), immune signaling (i.e. TNFRSF14), and BCR/NFKB signaling (e.g. CARD11, CD79B) were previously reported in follicular lymphoma cases." (PMID 35795062, 2022). "As expected, mutations in frequent drivers such as CREBBP, KMT2D,TNFRSF14 and RRAGC were more frequent among follicular lymphomas, those of MYC, CCND3 and ID3 prevailed among Burkitt lymphoma and those of BTG2, PIM1, SGK1 and SOCS1 were more frequent among DLBCL." (PMID 33945543, 2021).
Hepatic steatosis (4 papers, 2018 to 2024). Steatosis is a term used to denote lipid accumulation within hepatocytes. "In conclusion, the observed phenotype of overweight NAFLD patients with non-elevated levels of TG and HOMA-IR, which is associated with genetic variants of SOCS1, provides a rationale for further research on the pathophysiology of fatty liver disease." (PMID 31717271, 2019). "The observation that a distinctive phenotype of NAFLD may be associated with a genetic variant of SOCS1 justifies further investigation of the pathophysiology of fatty liver diseases." (PMID 31717271, 2019). "In conclusion, QHF can significantly alleviate hepatic steatosis and inflammation in NASH mice by upregulating SOCS1 to inhibit the TLR4/NF-κB signaling pathway." (PMID 33293985, 2020). "In addition, negative inflammatory mediators such as SOCS1 and SOCS3 contribute to hepatic steatosis, inflammation, and fatty necrosis." (PMID 30365523, 2018).
hepatoblastoma (4 papers, 2013 to 2022). Hepatoblastoma (HB) is a malignant hepatic tumor and is the most common pediatric liver cancer. "As a result, aberrant DNA methylation at the APC, CDH1, MT1G, RASSF1A and SOCS1 promoters were reported in hepatoblastoma." (PMID 36212481, 2022).
injury (4 papers, 2014 to 2025). Damage inflicted on the body as the direct or indirect result of an external force, with or without disruption of structural continuity. "Exogenous SOCS-1 adenovirus (Ad-SOCS-1) administration exhibits protective effect against bleomycin-induced pulmonary inflammation and fibrosis as well as hyperoxic acute lung injury." (PMID 32106541, 2020).
malaria (4 papers, 2018 to 2022). Malaria is a serious and sometimes fatal disease caused by a parasite that commonly infects a certain type of mosquito which feeds on humans. "Furthermore, we showed that SOCS1 expressions were reduced in Stat1−/− cDCs and splenocytes treated with malaria gDNA and RNA, but completely abolished in Stat1−/− cells with IFN-α/β stimulation." (PMID 30470758, 2018). "However, SOCS1 deficiency could not protect host from infection in Myd88−/− mice, suggesting that SOCS1 controls the host resistance to malaria mainly through MyD88-mediated IFN-I production." (PMID 33363057, 2020). "Remarkably, immunoregulatory molecules like SOCS1 and SOCS3 were found altered in each malaria sub-groups by the fold change value of 4.04 and 1.88 in UC1 while 4.55 and 3.12 in severe case group, respectively, compared to endemic control." (PMID 31614626, 2019). "During malaria, AIM2 and NLRP3-induced CASP1-dependent inflammasome signaling induces the release of IL-1β in pDCs and activates IL-1 signaling, which induces negative regulator SOCS1 in a MyD88-TRAF3-IRF3-dependent manner and inhibits MyD88-IRF7-dependent type I IFN signaling in pDCs." (PMID 36214572, 2022).